BRAF (B-Raf proto-oncogene, serine/threonine kinase)
Diseases named in the same sentence as BRAF in open-access papers (continued):
Sharing a sentence is not in itself a finding about the gene and the disease.
tumor (continued). "By examining the expression levels of Ng2 in tumor tissues of BRAF-mutant mice aged 3 weeks to 12 weeks, we found that its expression increased with tumor progression." (PMID 38795180, 2024). "Several clinical and biological factors are utilized for both clinical-prognostic stratification and therapeutic targeting in metastatic CRC, including initial tumor burden, CEA levels, performance status, BRAF and RAS mutations, and microsatellite status." (PMID 38291479, 2024). "Next-generation sequencing (NGS) analysis detected MSI-H, tumor mutation load (TMB) of 17.06 mutations/Mb, and wild-type status for BRAF/NRAS/KRAS, with mutations in β2M and LRP1B." (PMID 39193390, 2024). "For instance, studies have shown a significant increase in promoter methylation of the TSHR gene in BRAF-mutated PTC samples, leading to gene silencing and subsequent tumor progression." (PMID 38949925, 2024). "Nearly a decade ago, it was shown that MSI status can be determined from microsatellites covered by tumour gene panel, exome, and/or genome sequencing, in parallel with other genetic biomarkers such as BRAF c.1799T>A." (PMID 38962168, 2024). "The availability of tumor gDNA for a majority of KIAA1549::BRAF fusion cases in our cohort allowed us to verify a concordance between BRAF CNV values and the number of copies of fusion ctDNA." (PMID 38371226, 2024). "Mutational status of BRAF, RAS, and SMAD4 in tumor tissue from mCRC patients candidate for liver metastasectomy should be considered to select those patients with a higher chance of benefiting from the surgical treatment." (PMID 39220128, 2024). "The common combination of a BRAF inhibitor with a MEK inhibitor significantly shrank tumours, with reductions of 70% to 100% in many cases, and up to 91% for those treated before surgery." (PMID 39456573, 2024). "Several tumors harboring genomic alterations with FDA-approved indications in other tumor types were found including pathogenic PIK3CA, EGFR Exon 19/20 insertions, KRAS G12C (N = 1), FGFR fusions (N = 1), BRAF V600E mutations (N = 4), and BRCA2 (N = 1)." (PMID 39191445, 2024). "When injected into the posterior fossa, only the BRAF VE kin elicited tumours with a strong resemblance to pilocytic astrocytomas." (PMID 39324445, 2024). "Some tumour types have a combination of their typical molecular alterations, like BRAF V600E in ganglioglioma, to which H3K27M appears superimposed." (PMID 39126064, 2024). "Next, we assessed the analytical performance of DELFI-TF for measuring tumor burden in patients with RAS/BRAF mutant tumors using ddPCR for MAF quantification." (PMID 39433569, 2024). "We performed a series of tumor gDNA dilutions using gDNA from patient 11 with 33% BRAF fusion as ascertained by ddPCR using a fusion-specific probe." (PMID 38371226, 2024). "Tumor molecular burden (TMB) appears to be higher in BRAF non-V600E mutant NSCLC, though programmed death-ligand 1 (PDL-1) expression is more often <50%." (PMID 39684685, 2024). "AXL expression is also correlated with acquired MAPK resistance, including BRAFi/MEKi double resistance, and targeting AXL cooperatively inhibited tumor growth with BRAF/MEK inhibitors in patient-derived xenografts." (PMID 38732242, 2024). "Although cetuximab in combination with FOLFOXIRI can significantly increase the depth of tumor response for RAS/BRAF wild-type patients with initially unresectable CRLM, this improvement did not translate into superior ORR or R0 resection rates." (PMID 38728364, 2024).
tumor (continued). "Further, we compared the effects of each pUMAP cluster on genes associated with critical HT29 tumor biomarkers: KRAS, BRAF, CDH1, CYNNB1, and MET." (PMID 39605490, 2024). "Despite the low histological grade and radical surgical treatment of the tumor at primary manifestation, the disease had aggressive clinical course and the response to BRAF/MEK targeted therapy administered at recurrence was complete but nondurable." (PMID 39018206, 2024). "Numerous studies have demonstrated a robust oncogenic function of the genetic duets of BRAF/RAS mutations and TERT promoter mutations in driving tumor aggressiveness and poor clinical outcomes of PTC." (PMID 38735658, 2024). "On the contrary, another study suggests that MM visceral metastases of the BRAF genotype are rather heterogeneous and cannot be predicted based on primary tumor findings." (PMID 38541077, 2024). "Despite being initially effective, therapies inhibiting BRAF V600E are often limited by the development of drug-resistant tumor subpopulations in the TME." (PMID 39336897, 2024). "Our study revealed significant dynamic changes in BRAF, APC, and GNAS mutations during ICI treatment, shedding light on the tumor’s molecular evolution under therapeutic pressure." (PMID 39796090, 2024). "Significant differences in the prevalence of potentially targetable genomic alterations (ATM, BRAF, BRCA2, ERBB2, IDH1, PIK3CA, and PTEN) were observed in MTAP-loss tumors and varied according to tumor type." (PMID 38330461, 2024). "Currently all reported use of BRAF inhibitors in BRAF V600 E positive PCP has shown a positive response in reducing tumor size." (PMID 39634188, 2024). "Of the patients who had genomic profiling performed on both tumor and ctDNA samples, 368 of 404 (91.1%) had BRAF-V600E detected in both." (PMID 39313594, 2024). "While KRAS-mutated tumours displayed decreased immune cell infiltration compared to KRAS wild-type tumours, the opposite was found for BRAF-mutated tumours, differences that were most obvious for the cytotoxic T cells and the Th1 cells." (PMID 38040818, 2024). "Targeting BRAF fusions clinically with an MEK inhibitor or BRAF inhibitors has been reported in multiple tumor types." (PMID 38791940, 2024). "IHC experiments displayed that the positive expressions of Ki67(a well-known marker of cell proliferation), OTUD4, CDK1, FGFR1 and p-BRAF were obviously decreased in tumor xenografts with OTUD4 knockdown." (PMID 38429268, 2024). "In contrast, BRAF mutant tumors had significantly reduced tumor stem cell and TA cell populations compared to Min tumors (BLM2 vs. Min)." (PMID 38893159, 2024). "Our findings are also supported by a previous study on BRAF and NRAS mutation frequencies among primary tumours and their paired metastasis describing a 15% discrepancy in mutational status." (PMID 38127894, 2024). "The background of high genome methylation observed in CIMP is hence a pre-requisite for mutant BRAF to be pro-tumorigenic; this is what is thought to foster the development of BRAF-driven CIMP tumours." (PMID 38540202, 2024). "The combination of BRAF and tyrosine kinase (TK) inhibitors has been demonstrated to be highly effective in inhibiting tumor development and is an approach for overcoming resistance in clinical trials." (PMID 39281035, 2024). "CFT1946, an oral PROTAC, demonstrated promising anti-tumor activity in BRAF (V600X) preclinical models." (PMID 39500878, 2024). "We aimed to investigate the AF of BRAF V600E and TERT mutations in intermediate-to-high risk PTC and their association between tumor invasiveness, prognosis, and other mutations." (PMID 38607456, 2024).
tumor (continued). "A more extensive study of 79 dogs with UC of the urinary bladder or urethra found a trend towards shorter MST in dogs with BRAF p.V595E versus BRAF wildtype tumours (214 versus 359 days, p = 0.055)." (PMID 38787171, 2024). "While the experience of genetics-guided therapy is limited in NEC, the European Neuroendocrine Tumor Society (ENETS) 2023 guidelines recommend that BRAF-inhibitor combinations should be considered as a possible treatment in case of BRAF-mutated tumors." (PMID 38716076, 2024). "It is also known that V600E mutant BRAF plays a critical role in maintaining the functions of tumor cells." (PMID 38791574, 2024). "Evidence from several case reports suggests that BRAF/MEK inhibitors produce efficient tumor shrinkage in the first 3 months of therapy." (PMID 39634188, 2024). "This discovery has opened the way for the potential use of BRAF inhibitors in the treatment of this tumor, such as vemurafenib and dabrafenib." (PMID 39274556, 2024). "With advancements in liquid biopsy and sequencing technologies, several research teams have analysed circulating tumour DNA (ctDNA) or tumour tissue from patients with acquired drug resistance to BRAF‐targeted therapy." (PMID 39073010, 2024). "Combination therapy with a BRAF inhibitor and a MEK inhibitor (BRAF/MEKi) has been proven to improve ORR, prolong PFS and OS, and reduce the frequency of secondary tumor development compared with a BRAF inhibitor alone." (PMID 38087810, 2024). "The AF of BRAF V600E shows potential as a novel indicator for predicting tumor invasiveness and prognosis." (PMID 38607456, 2024). "Tumours should be reflexively tested for MMR deficiency, with MMR deficient tumours further tested for MLH1 promoter methylation and/or BRAF c.1799T>A (p.V600E) to exclude sporadic MMR deficient CRCs from the screening pathway." (PMID 38962168, 2024). "The coexistence of BRAF and NRAS mutations was noted in eight tumor specimens, while seven samples tested as wild-type (WT) for both BRAF and NRAS genes." (PMID 38396984, 2024). "RET fusion-positive carcinomas were associated with aggressive tumor behavior, including high rates of lymph node (75.2%) and distant metastases (18.6%), significantly higher than in NTRK fusion, BRAF V600E and RAS-positive carcinomas." (PMID 37882481, 2023). "Many important steps have already been made in the selection of chemotherapy according to the molecular pattern of the tumours, especially in the case of RAS and BRAF mutations." (PMID 36674640, 2023). "Univariate analyses revealed that old age (≥55 years), tumor size, ETE, BRAF mutation, MLN number, and high LNR (≥0.75) were the main factors that influenced STRFS (p<0.10)." (PMID 37790606, 2023). "Anti-tumor treatment was initiated with a combination therapy of BRAF inhibitor dabrafenib and MEK inhibitor trametinib." (PMID 38074649, 2023). "Mutational analysis demonstrated concordance with the primary tumor pathology analysis (extended RAS and BRAF V600 clinical testing) and the observed organoid mutations." (PMID 37565053, 2023). "By inspecting their oncoprint, 27/59 tumours harboured mutations in either SOX9 or MYC and were wild-type in either BRAF, KRAS or NRAS, hinting towards an alternative cetuximab resistance mechanism." (PMID 37666855, 2023). "We conducted a cross-sectional study of the KRAS and BRAF mutational landscape of patients with CRC, whose tumor specimens were analyzed at a single institution." (PMID 38139338, 2023). "This reduction in tumor size after BRAF-directed therapy corresponded to a reduction in extent of surgery and surgical morbidity." (PMID 36762947, 2023).
tumor (continued). "Several reports showed that a combined targeted therapy, with both BRAF and MEK inhibitor agents, seems to have a better efficacy in terms of tumor volume reduction and rapidity of actions than a single BRAF inhibitor." (PMID 36979325, 2023). "The spectrum of BRAF alterations is still expanding because of the increasing sequence coverage of tumor genomes." (PMID 37656784, 2023). "This is because BRAF inhibitors are supposed to modulate the tumor immune microenvironment by increasing interferon-gamma production on intratumoral CD4+ T lymphocytes and increasing CD8+ TILs." (PMID 37569757, 2023). "MEKi and anti-PD1 treatment in the BRAF wild-type subgroup induced a high tumor control rate of 83% and a median PFS of 7.1 months." (PMID 36983983, 2023). "We see the use of BRAF Inhibitors to reduce tumor size with consecutive surgical treatment as a reasonable option for therapy." (PMID 37115331, 2023). "If the tumor is left-sided, RAS, or BRAF wild-type, you should check that the patient did receive prior anti-EGFR therapy and that patients with dMMR or BRAF V600E mutated tumors have been exposed to immunotherapy and BRAF inhibitors, respectively." (PMID 38201553, 2023). "When possible, this molecular phenotype should be addressed by NGS-based assays, as they allow for the simultaneous estimation of tumor mutational burden, the detection of mutations in the MMR and BRAF genes, and the assessment of copy-number status." (PMID 38344144, 2023). "Of 672 patients included, 226 (33.6 per cent) had RAS&BRAF wild-type (wt) tumours, 392 (58.3 per cent) RAS mutation (mt) tumours, and 54 (8.0 per cent) BRAFmt tumours." (PMID 36511370, 2023). "This analysis revealed subtype-specific signatures of metabolic genes in PTC, leading to the identification of Hif-1α as one the main transcriptional contributors to the metabolic rewiring of BRAF-driven tumours." (PMID 37198319, 2023). "Altogether, these observations indicated that equally sparse activation of mutant BRAF manufactured by leaky Cre activity generated striking tissue differences in tumor development." (PMID 37534159, 2023). "In another study, the metastasis of a primary tumor bearing an immunogenic BRAF clonal neoantigen (V599E) induced an HLA-restricted cytotoxic T cell response to the clonal BRAF neoantigen in the metastatic lesion as the inciting event." (PMID 38067319, 2023). "Ras-Raf-MEK-ERK dysregulation has been reported to contribute to the development of several tumor types due to mutations in constituent proteins of this pathway, including RAS (KRAS and NRAS) and RAF (BRAF)." (PMID 37834222, 2023). "As 20–25% of the aggressive ATC cases display BRAFV600E mutation, we sought to verify, likewise reported in BRAF-driven PTCs, the presence of a BRAF-mediated glycolytic phenotype in this tumor and if B-raf inhibitors are able to restrain it." (PMID 37198319, 2023). "A 50% increase on testing across each step of the testing pathway (MMR tumour testing, methylation or BRAF testing, and constitutional genetic testing) compared with baseline level measured by NDRS." (PMID 39886501, 2023). "Genomic analysis indicated that RNF43 mutation affected the genomic characteristics of patients with BRAF mutation, including microsatellite instability (MSI), tumor mutation burden (TMB) and the proportion of common gene mutations." (PMID 37409251, 2023). "The most prominent tumor‐related alterations in the v‐RAF B1 (BRAF) gene for the murine sarcoma viral oncogene." (PMID 37675821, 2023). "7c has high activity against BRAF-V600E with an IC50 of 31 nM and effectively inhibits ERK phosphorylation in tumor cell lines bearing BRAF-V600E." (PMID 36770611, 2023).
tumor (continued). "Synergy between MEK inhibition and BH3 mimetics was previously reported in other tumor types where it was shown that RAS and BRAF mutations have destabilizing effects on BIM." (PMID 36895472, 2023). "Our study found that the level of tumour inflammation markedly affected the sensitivity of the AI-based BRAF prediction, which was low for inflamed UC and high in those without associated inflammation." (PMID 37570213, 2023). "But a significantly better mOS (high tumor infiltration CD68+ macrophages vs. low tumor infiltration CD68+ macrophages cases, 26 vs. 15 months, P = 0.002) was observed in BRAF wide-type mCRC with higher tumor infiltration CD68+ macrophages." (PMID 37302081, 2023). "Patients with KRAS, NRAS, PIK3CA and BRAF wild-type tumours were randomised between the pan-HER inhibitor AZD8931 and placebo." (PMID 35256486, 2023). "OS rates at 7.5 years were 57%, 42%, and 25% in patients with BRAF-mutant tumours and 43%, 41%, and 21% in patients with BRAF wild-type tumours in the nivolumab–ipilimumab, nivolumab, and ipilimumab treatment arms, respectively." (PMID 37404764, 2023). "In our study, REC8 showed significant hypermethylation in tumor tissue for the BRAF wild-type group when compared to the BRAF mutant group." (PMID 36975440, 2023). "CIMP-high CRCs are associated with older-age patients, female sex, proximal tumor location, MSI-H status, and somatic BRAF mutation." (PMID 39132649, 2023). "In addition to the BRAF mutation, poorly differentiated (PDTCs) and anaplastic thyroid cancers (ATCs) often have other genetic and/or non-genetic alterations that can lead to the activation of certain signaling pathways involved in cancer cell growth and tumor progression." (PMID 36982542, 2023). "Multivariate analyses showed that tumor size, ETE, BRAF mutation, MLN number, and high LNR (≥0.75) were independent influencing factors for STRFS (p < 0.05)." (PMID 37790606, 2023). "Specific tumor cells can rapidly adapt to the presence of BRAF/MEK inhibitors by turning on a feedback mechanism that can reestablish MEK/ERK signaling, which is often mediated through a receptor tyrosine kinase (RTK) signaling pathway." (PMID 37834284, 2023). "Bevacizumab, a humanized monoclonal antibody that targets vascular endothelial growth factor (VEGF), is the only biologic option for RAS/BRAF mutant tumours." (PMID 36674640, 2023). "Several other Phase I and II studies using BRAF-inhibitors (dabrafenib and vemurafenib) have shown anti-tumor activity in a portion of patients with progressive BRAFV600E-mutant PTC." (PMID 36624452, 2023). "Tuba-seq analysis of DNA extracted from bulk tumor-bearing lungs allowed us to quantify tumor burden and size across mouse genotypes, and thus determine the tumorigenic potential of BRAF V600E and EGFR L858R relative to KRAS G12C and KRAS G12D." (PMID 37828026, 2023). "Compared with NP (siControl), NP (siBRAF) showed a 60% reduction in BRAF protein expression and a threefold reduction in tumor size." (PMID 37833748, 2023). "Five of these tumours had a BRAF mutation, four had the hotspot V600E mutation and one had a CICD2‐BRAF fusion." (PMID 37317665, 2023). "The role of BRAFV600E signaling in the regulation of tumor metabolism suggests that BRAF can generate biodynamic adaptation by inhibiting oxidative phosphorylation." (PMID 37853445, 2023). "The phase 3 BRIM-3 trial showed that BRAF-targeted therapy had a rapid onset of action; tumor responses were seen by the first 2 months of therapy and occurred more rapidly than the responses to cytotoxic therapies." (PMID 36801912, 2023).